NPM1 (nucleophosmin 1)
Diseases named in the same sentence as NPM1 in open-access papers (continued):
Sharing a sentence is not in itself a finding about the gene and the disease.
cancer (continued). "We further tested the cancer cell invasion ability by Transwell assays, and the results revealed that NPM1 upregulation was positively correlated with the invasion ability of PCa cells." (PMID 37875480, 2023). "Many studies have reported that FHL1 undergoes epigenetic regulation by promoter methylation in various cancers, and NPM1 plays an important role in epigenetic regulation." (PMID 35142956, 2023). "Knockdown of NPM1 reduced the growth rate and invasion ability of PCa cells, whereas increasing NPM1 expression accelerated cancer cell proliferation and invasion." (PMID 37875480, 2023). "Of these, HSPA8, HSPA9, PKM, HNRNPA1, NPM1, ANXA2 are already reported to be associated with LN metastasis in GBC or other cancers." (PMID 37142981, 2023). "We found that the ribosome biogenesis was disrupted and NPM1 dispersed in the nucleoplasm in Puf-A-silenced cancer cells." (PMID 34999733, 2022). "The role of NPM1 as a proto-oncogene is supported by the observation that cancer cells in the phase of growth and proliferation overexpress NPM1, and at the same time, apoptosis is inhibited." (PMID 35054502, 2022). "In order to further explore the relationship between NPM1 expression and gastrointestinal cancer, we analyzed the relationship between NPM1 expression and pathological characteristics of cancer patients." (PMID 36188614, 2022). "The role of NPM1 in human cancer is remarkable for its involvement in tumors of diverse histological origins." (PMID 35054502, 2022). "NPM1 that exerts pleiotropic and trophic roles is hijacked by transforming mechanisms to sustain the growth of cancer cells." (PMID 35085325, 2022). "More importantly, NPM haploinsufficiency in NPM+/− mouse embryonic fibroblasts that mimic cancer cells harboring chromosomal rearrangements/deletions at the NPM1 locus shows an immortal phenotype with high proliferation." (PMID 36280841, 2022). "This study shows that NPM1 is highly expressed in gastrointestinal cancers, and its expression level can accurately diagnose cancer, and is a prognostic indicator of ESCA, LIHC, and PAAD." (PMID 36188614, 2022). "Here, we examined Puf-A expression and its correlation with clinical outcome in lung and colorectal cancers, investigated its transcriptional regulation, and elucidated its role in cancer proliferation, at least in part via interaction with NPM1." (PMID 34999733, 2022). "As a well‐known nucleolar phosphoprotein, NPM1 has been found to be strongly correlated with cell proliferation and cancer pathogenesis." (PMID 34469024, 2021). "The role of NPM1 in regulating mitosis was corroborated in different studies showing that cancer cells undergoing mitosis have a high level of NPM1 phosphorylated on Thr199 predominantly localized to the cytoplasm and the centrosome of dividing cells." (PMID 34201061, 2021). "This interaction allows HIF‐1 to select and stably bind to HRE‐containing promoters, making NPM1 an essential coactivator of hypoxia target genes, a role also supported by analysis of cancer patient data." (PMID 34388291, 2021). "Eventually, we showed that this mutual interaction between LETN and NPM1 is essential for the proliferation of cancer cells and potentially NPCs." (PMID 33432115, 2021). "Among this network, NPM1, a nucleolar multi-functional protein frequently deregulated in cancer, emerged as another potential target related to treatment resistance in DLBCL." (PMID 34885010, 2021). "Through the analysis of Oncomine database, we found NPM1 was overexpressed in 9 types of cancer, and analysis of the TCGA data set found that NPM1 was overexpressed in 13 types of cancer, which was consistent with the results of previous studies." (PMID 34335635, 2021). "Dysregulation of NPM1 has been observed in various human cancers in which it promotes or inhibits the development and progression of cancer." (PMID 32378344, 2020).
cancer (continued). "Hereafter we provide an update of the most investigated or promising compounds and what is currently known on their effectiveness in targeting NPM1 in cancer." (PMID 32664415, 2020). "The NPM1 expression level is increased in cancer cells, which qualitatively suppresses p27 function and promotes cell proliferation of cancer cells in vitro and in vivo." (PMID 33050036, 2020). "We isolated nucleophosmin isoform 1 (NPM1), which is highly expressed in variety of cancers, as a novel p27-interacting protein." (PMID 33050036, 2020). "We identified NPM1, which is highly expressed in cancer cells, as a novel factor interacting with p27 and confirmed that the increased expression of NPM1 in cancer cells suppresses p27 function and promotes cell proliferations in vitro and in vivo." (PMID 33050036, 2020). "We suggest the mechanism as a novel mechanism of suppressing p27 function and NPM1 is a potential target for cancer treatment to recover p27 function." (PMID 33050036, 2020). "As to now, these trials are focused on the treatment of hematologic malignancies and other types of cancer, however, the contribution that NPM1 plays in the life cycle of many viruses suggests the investigational use of NPM1 inhibitors also as antivirals." (PMID 32664415, 2020). "The efficacy of novel APE1/NPM1 interaction inhibitors, which sensitize cancer cells to chemotherapy agents, supports the translational importance of these findings." (PMID 31913336, 2020). "By proteomic screening for factors interacting with p27, we identified nucleophosmin isoform 1 (NPM1) as a novel p27-interacting factor and observed that NPM1 protein was expressed at high levels in some cancer cells." (PMID 33050036, 2020). "Our findings reveal that NPM1 is a novel p27 functional suppressor and a potential anti-cancer target, especially in cancers with normal p27 expression." (PMID 33050036, 2020). "A proof of concept for the relevance of APE1 PPIs in cancer biology is represented by the paradigmatic example of the APE1-nucleophosmin 1 (NPM1) interaction, as ascertained by us18." (PMID 31913336, 2020). "We checked the expressions of NPM1 in normal cells and cancer cells and observed that the protein level of NPM1 is about two times higher in cancer cells than normal cells." (PMID 33050036, 2020). "Surprisingly, they affected NPM1 oligomerization both in vitro and within several cancer cell lines." (PMID 32664415, 2020). "NPM1 overexpression in normal cells suppressed p27 function, and conversely, NPM1 knockdown in cancer cells restored the function in vitro." (PMID 33050036, 2020). "Overexpressing NPM1 in normal cells suppressed and silencing NPM1 in cancer cells rescued the p27 function, respectively, in vitro." (PMID 33050036, 2020). "Conversely, NPM1 knocked down cancer cells showed a lower growth rate than the control cancer cells upon p27 induction." (PMID 33050036, 2020). "This list of commonly mutated cancer genes contained 3 centrosome genes: CEP76, CTNNB1, and NPM1, which were included in our analysis." (PMID 32681070, 2020). "NPM1 haploinsufficiency contributes to the development of some cancers such as AML, but preliminary findings in murine models suggest that it does not contribute to the development of ALCL." (PMID 31366041, 2019). "APE1 and NPM1 protect cancer cells from Pt-compounds cytotoxicity, suggesting a possible improvement of the activity of Pt-based therapy for TNBC, using the NPM1 and APE1 proteins as secondary therapeutic targets." (PMID 31307523, 2019). "Growing evidence has shown overexpression of NPM1 in various cancers and its correlation with poor prognosis." (PMID 31462227, 2019). "In two transplantation lines (descending from C25 and E31) we observed the occurrence of new mutations in genes described as cancer drivers in COSMIC-CGC database, which are Rhoh, Npm1, Elf4, Ikbkb, and Nutm1." (PMID 30262843, 2019).
cancer (continued). "Many mutated genes from transplanted tumors encode proteins important for cell adhesion and transcription, among them the COSMIC-CGC cancer drivers Npm1, Nutm1, and Elf4." (PMID 30262843, 2019). "This network centers on the NF-κB transcription factor complex, ribosomal proteins, and NPM1 protein, which together mediate signals relevant to cell survival, cancer progression, and inflammation." (PMID 29481576, 2018). "In accordance, NPM1 has been reported to be overexpressed at the protein level in various solid tumors and in some cases it has been proposed as a cancer-specific marker." (PMID 29221119, 2017). "In a disease setting, the balance between NPM1 expression and cell fate is demonstrated in hypoxia-driven cancers." (PMID 27553022, 2016). "If we aim at successfully targeting NPM1 for cancer treatment we will also need to address these important issues." (PMID 27058426, 2016). "Such molecules were tested against a significant panel of cancer cell lines where NPM1 is overexpressed and showed significant activity, especially in combination with other drugs (NSC34884) or radiation (YTR107)." (PMID 27058426, 2016). "Given the critical role NPM1 plays in genome stability and apoptosis it is hardly surprising that NPM1 dysfunction is a frequent feature in cancers." (PMID 27553022, 2016). "A comprehensive description of the pleiotropic functions played by NPM1 and its role in cancer has been the subject of a number of excellent reviews to which we refer the reader." (PMID 27058426, 2016). "This leads to the expression, in the cytoplasm of cancer cells, of a chimeric protein consisting of the NPM1 N-terminal oligomerization domain fused to the ALK tyrosine kinase domain." (PMID 27058426, 2016). "Synthetic peptide CIGB-300 (also called p15-Tat) has been described as a proapoptotic and anti-cancer peptide, which directly targets and antagonizes NPM1 function in cancer cells." (PMID 26624888, 2015). "Overall, high expression of NPM1 is common in rapidly and continuously proliferating cells and cancer cells." (PMID 26068981, 2015). "Several different types of cancer cells with elevated levels of NPM1 are also more resistant to UV or hypoxia induced apoptosis than those with low expression." (PMID 26559910, 2015). "In summary, this study demonstrates a novel structural co-expression network analysis platform, which allows for the establishment of a cooperativity model for exploring cancer pathogenesis and its potential NPM1-oriented treatment exploration." (PMID 26205693, 2015). "NPM1 is a nuclear phosphoprotein which plays a variety of roles in cancer cells by affecting DNA repair, centrosome duplication, and molecular chaperoning." (PMID 25617756, 2015). "NPM1 (nucleophosmin) is a multifunctional chaperone that plays an important role in cancer development." (PMID 26559910, 2015). "The significance of NPM1 as a cancer gene was somewhat dubious because it was thought that the NPM1 part (of the fusion protein) was only used an essential dimerization interface." (PMID 21152184, 2011). "Consequently, disruption of these interactions has emerged as a viable strategy to inhibit the specific functions of NPM1 in cancer cells." (PMID 41234771, 2025). "Currently, inhibitors aimed at blocking NPM1 in cancer cells are under development." (PMID 40705480, 2025). "Additionally, NAT10 promotes PD-L1 transcription in various cancers by facilitating NPM1 acetylation, which correlates with poor patient prognosis." (PMID 40109769, 2025).
cancer (continued). "This study validated that NPM1 promoted the transcription of PD-L1 in different cancer types." (PMID 38243170, 2024). "Additionally, NPM1, a multifunctional histone chaperone, is often overexpressed in various human cancers." (PMID 38831454, 2024). "The ability of NPM1 to promote cancer cell migration and invasion has been verified in vitro." (PMID 38164189, 2024). "Notably, analyses such as TDMDscore (0.5055), phylop (4.336), and Pan-Cancer indicate its stronger RNA-RBP binding with NPM1, higher conservation across different species, and its involvement in diverse diseases and cancers." (PMID 38662949, 2024). "This study suggests that the NAT10/NPM1 axis is a promising therapeutic target in malignant tumors." (PMID 38243170, 2024). "Moreover, in cancer cells, an acetylated form of NPM1 (acNPM1) functions as a coactivator of RNA polymerase II-dependent transcription to promote the expression of genes involved in tumorigenesis." (PMID 37759327, 2023). "Full-length (FL) NPM1 self-assembles into large oligomers in isolation and in cancer cells." (PMID 36743470, 2023). "NPM1, abundant nucleolar proteins that often shuttle between the nucleolus and the nucleoplasm or cytoplasm, is involved in chromatin remodeling, genome stabilization, cell cycle progression, and apoptosis in cancer." (PMID 38097352, 2023). "The role of NPM1 in cancer cells, especially PCa cells, remains elusive." (PMID 37875480, 2023). "Based on the significant fold change in LN positive GBC in mass spectrometric data and literature survey for their functional relevance and association with LN metastasis in cancer, we selected four proteins namely KRT7, KRT19, SRI and NPM1 for verification using Western blot analysis." (PMID 37142981, 2023). "Since c-Myc is regulated by NPM1 in PCa cells, and that c-Myc is a well-known oncogene driving multiple cancers, including PCa, we hypothesize that the oncogenic function of NPM1 in PCa is performed through a c-Myc-mediated pathway." (PMID 37875480, 2023). "Interestingly, we did not observed difference between the HA-EV and HA-NPM1 groups when treated with JQ1, which is consistent with the previous result that NPM1 regulated cancer cell growth through BRD4." (PMID 37875480, 2023). "Whether Puf-A interacts with NPM1 in the nucleolus to affect the proliferation of cancer cells is unclear." (PMID 34999733, 2022). "Therefore, it is believed that the cancer-promoting activity of NPM1 gene is related to the expression of genes related to m6A." (PMID 36188614, 2022). "Furthermore, we previously showed that in cancer cells, Puf-A interacted with NPM1 in nucleolus, based on studies of immunofluorescence staining and immunoprecipitation." (PMID 35563782, 2022). "Multiple cancer-associated genes are significantly downregulated in the translatome upon shMSI1 inhibition, including MAP3K13, transcriptional enhancers of MYC and genes essential in early development, NPM1 and KMT2A, respectively." (PMID 36473869, 2022).
cancer (continued). "Thus, it is possible that the overexpression of NPM1 in cancer cells increases cell growth and proliferation primarily by providing ribosomes." (PMID 35054502, 2022). "NPM1 functions are often related to the last steps in ribosome processing and assembly with r-proteins, but also several other functions of NPM1 were described: regulation of centrosome duplication, genome stability, stress response, apoptosis, cancer, and rRNA gene remodeling." (PMID 34884901, 2021). "Indeed, the data mining process with GEPIA2 for analysis of NPM1 mRNA levels in 33 different human cancer types revealed that NPM1 expression is significantly higher in 11 types of human tumors in comparison to paired normal tissues." (PMID 34388291, 2021). "Furthermore, overexpression of NPM1 also promoted the migration and invasion of cancer cells even though KPNA2 was repressed." (PMID 34469024, 2021). "Moreover, three of the ‘hypoxic’ cancer types were the same as the ones exhibiting significantly high expression levels of the 67 NPM1/HIF‐1α‐dependent gene signature (namely, DLBC, GBM, and THYM)." (PMID 34388291, 2021). "We believe that the cancer promoting effect of NPM1 gene is related to the modification of m6A, which may affect the methylation level of LUAD through its association with HNRNPC, and ultimately affect the progression of LUAD." (PMID 34335635, 2021). "Remarkably, both the 67 NPM1/HIF‐1α‐dependent gene signature gene and the hypoxic gene signatures were associated with poor prognostic outcome in the cohort of patients with DLBC, GBM, or THYM cancer types." (PMID 34388291, 2021). "Based on the expression of this hypoxic gene signature, five out of the 11 cancer types with high NPM1 could be characterized as ‘hypoxic’." (PMID 34388291, 2021). "NSC348884, a specific inhibitor of NPM1, binds to NPM1 and specifically disrupts the hydrophobic pocket structure of the amino terminus, thereby inhibiting the formation of oligomers and disrupting their abnormal function in cancer cells." (PMID 34899858, 2021). "In summary, elucidating how NPM1 abnormalities and/or aberrant nucleocytoplasmic shuttling contributes to tumor progression is emerging as a need for developing innovative targeting strategies for the improvement of cancer therapy." (PMID 34340703, 2021). "While analyzing multiple cancer disorders, we found highly variable expression among genes implicated in cancer: EEF1A1, GNAS, NPM1, PIM1, and RHOA are known oncogenes; H3F3A, PTPRC, SMARCB1, and B2M are possible oncogenes; and CASP8, JAK1, and PRKAR1A are known tumor suppressor genes." (PMID 34174938, 2021). "Repression of LETN or NPM1 led to similar and profound changes of the nucleolar morphology and arrest of the nucleolar functions, which led to proliferation inhibition of human cancer cells and neural progenitor cells." (PMID 33432115, 2021). "In addition, the detailed mechanism of KPNA2 and NPM1 as an oncogenic factor in cancer cells should be evaluated in future studies." (PMID 34469024, 2021). "In these 11 cancer types, NPM1 expression is positively correlated with expression of HIF1A but not with EPAS1 which encodes HIF‐2α, in line with our data showing that NPM1 interacts only with the HIF‐1α isoform." (PMID 34388291, 2021). "Bioinformatics analysis was performed using R software package and other online databases to investigate differences in NPM1 expression in different cancers, and cell assay and immunohistochemistry (IHC) were used to verify differences in NPM1 expression between LUAD samples and normal samples." (PMID 34335635, 2021). "Furthermore, the tumors derived from cancer cells carrying the combination of p27 overexpression and NPM1 knockdown constructs showed significant suppression of growth as compared with those carrying other combinations in mouse xenograft models." (PMID 33050036, 2020).